USP2-AS1 (USP2 antisense RNA 1)
Synonyms: THY1-AS1; gLINC
Gene: Long non-coding RNA gene on chromosome 11 (119,356,467 to 119,659,284, forward strand). Ensembl gene ENSG00000245248.
Gene Ontology:
Molecular function: U4 snRNA binding
Biological process: formation of quadruple SL/U4/U5/U6 snRNP; spliceosomal tri-snRNP complex assembly
Cellular component: U4/U6 x U5 tri-snRNP complex; U6 snRNP
Diseases named in the same sentence as USP2-AS1 in open-access papers:
USP2-AS1 is named in the same sentence as 4 diseases in open-access papers, as found by Europe PMC text mining. Sharing a sentence is not in itself a finding about the gene and the disease. The quoted sentences say what the papers report.
colorectal cancer (1 paper, 2023). A primary or metastatic malignant neoplasm that affects the colon or rectum. "USP2AS1 is a cancer-promoting factor that promotes tumour progression by different mechanisms in various types of tumours, including ovarian and colorectal cancer." (PMID 36844873, 2023).
USP2-AS1 also shares sentences with these, for which no sentence is quoted: cancer (1 paper); liver cancer (1); tumour (1).